IL6 (interleukin 6)
Diseases named in the same sentence as IL6 in open-access papers (continued):
Sharing a sentence is not in itself a finding about the gene and the disease.
co-infection (continued). "In HIV/TB co-infection, combining miR-223-5p and miR-10 b-5p, which regulate Mtb growth and pro-inflammatory cytokines (e.g., IL-6, IL-8), achieved AUC = 0.96 (sensitivity 86.7%, specificity 91.7%), providing a specific co-infection marker." (PMID 41007639, 2025). "Both these studies highlight why IL-6 co-infection results obtained from this study should be increased compared to HNECs infected with IAV or PA alone." (PMID 40788668, 2025). "Our further ROC analysis confirmed that IL-6 and IL-10, individually and especially in combination, exhibit high sensitivity (>80%, and approximately 94% combined) for detecting co-infections." (PMID 40487016, 2025). "The presence of these co-infections was associated with significantly elevated inflammatory markers, including WBC count, LDH, IL-6, and IL-10, indicating more intense inflammatory responses." (PMID 40487016, 2025). "ELISA analysis of IL-6 contained in the supernatant indicated that co-infection of cells with both laboratory and clinical isolates of PA would lead to no significant change in inflammatory response compared to cells infected with the bacterial isolates alone." (PMID 40788668, 2025). "IL-6 and IL-10 are increased in kala-azar and HIV co-infection, while IL-6 is associated with severity signs and with the fatal outcome, similar to what is described in individuals with kala-azar without HIV." (PMID 41003560, 2025). "Multivariate analysis identified co-infection status, increased IL-6, and elevated CAR as independent predictors of severe outcomes." (PMID 39857695, 2025). "Interleukin-10 and IL-6 play a role in leprosy patients with helminth co-infections, which indicates that there is an influence of helminth infection on the immune responses of leprosy patients." (PMID 41239264, 2025). "The elevation in levels of plasma inflammation and microbial translocation biomarkers, especially soluble CD14 and interleukin-6 in people with HIV/HCV coinfection compared to PWH, have also been previously observed." (PMID 40006998, 2025). "We also show that co-infected HNECs exhibit lower IL-6 response when compared to HNECs infected with IAV alone, suggesting a novel finding where PA is dampening IL-6 response once co-infection occurs." (PMID 40788668, 2025). "The co-infection significantly increased IL-6 production compared to the mock control, and this increase was not affected by either vitamin D or DMSO." (PMID 40351306, 2025). "In co-infection scenarios, dysregulated IL-6 exacerbates lung damage and impairs bacterial containment." (PMID 40692679, 2025). "Lower levels of CD4+ and CD8+ cells and higher level of IL4 and IL6 in patients on the day of admission were significantly correlated with the development of coinfection the following days in the hospital." (PMID 40416960, 2025). "The nomogram was established based on the several inflammatory indicators and clinical characteristics, including age, preterm birth, underlying condition, seizures, NLR, IL-6, LDH, D-dimer, co-infection." (PMID 39114651, 2024). "These 16 candidate predictors were entered into multivariable logistic regression, eventually identifying nine independent risk factors, including age, preterm birth, underlying condition, seizures, NLR, IL-6, LDH, D-dimer, and co-infection." (PMID 39114651, 2024). "Nine strong predictors including age, preterm birth, underlying condition, seizures, NLR, IL-6, LDH, D-dimer, and co-infection were integrated into this model, which showed a good predictive ability, accuracy, and clinical usefulness." (PMID 39114651, 2024). "It has been reported that in an in vivo model of chemically induced carcinogenesis, the chronic co-infection of P. gingivalis and F. nucleatum activated the IL-6/STAT3 axis in the tongue epithelium, which in turn led to augmented tumor size and invasiveness." (PMID 38612423, 2024).
co-infection (continued). "In contrast, the co-infection of vL126A/ΔNLS with S. suis induced significantly lower-level expressions for IL-6, IL-8, TNFα, and IL-1α in comparison with the vWT and S. suis co-infection." (PMID 38547254, 2024). "Significant increases of IL-6, IL-8, TNFα, and IL-1α were observed in the vWT and S. suis co-infection group, compared to the vWT single-infection group, indicating that co-infection of PRRSV-2 and S. suis enhanced the proinflammatory cytokine expressions." (PMID 38547254, 2024). "Production and release of TNF-α, IL-6, and IL-10 protein 24 h after B. burgdorferi infection and coinfection was confirmed via ELISA." (PMID 37764937, 2023). "Subjects with plasmodial infection had only higher levels of IL-6 than subjects with P. falciparum/intestinal protozoa co-infection (P = 0.0008)." (PMID 35421083, 2022). "Following the co-infection we observed similar IL6 and IL8 level compared to the bacterial single infection." (PMID 35281454, 2022). "In patients who receive immunosuppressants such as interleukin-6 antagonists or glucocorticoids, the possibility of co-infection with bacteria, fungus, or virus is likely." (PMID 35448570, 2022). "In this study, we additionally report the regulation of proinflammatory (IL1-α, IL1-β, IL6, IL8, IL18, and TNF-α) and regulatory (IL10, IL22, IL23, and IL33) cytokines associated with single-PDCoV and -PEDV infection, as well as PDCoV/PEDV co-infection." (PMID 36376395, 2022). "Although both Il6 and Il10 were increased in the GAS and IAV+GAS group, respectively, only co-infection caused a significant secretion of the protein products." (PMID 36365071, 2022). "Next we plan to investigate if IL-6/IL-8 hypersecretion in the settings of HIV, TB infections and HIV/TB co-infection can predict morbidity and mortality associated with lung and other firms of cancer." (PMID 35804458, 2022). "The median TNF-α level and IL-10/IL-6 ratio were higher in subjects with STHs (p = 0.09) and P. falciparum-intestinal protozoa co-infection (p = 0.04), respectively." (PMID 35421083, 2022). "In detail, there is a difference in IL-6 and IL-8 levels when comparing the bacterial single infection or the co-infection with the corresponding mock infection." (PMID 35281454, 2022). "Authors plan to investigate if IL-6, IL-8 and IL-18 hypersecretion and reduced secretion of IL-17 in HIV, TB mono-infections and HIV/TB co-infections can predict morbidity and mortality associated with lung and other forms of cancer." (PMID 35804391, 2022). "The high IL-10/TNF-α and IL-10/IL-6 ratios observed here in participants with helminth co-infections are consistent with such observations." (PMID 35421083, 2022). "The level of IL-6 secretion in HIV/TB co-infection with newly diagnosed HIV, TB, and previously untreated HIV, both before the initiation of ART and during 6 months of therapy, remained constantly high." (PMID 34835417, 2021). "The persistent enhanced expression of IL-6 in patients with dual HIV/TB co-infection allows the consideration of it as a potential marker of early detection of M. tuberculosis infection in HIV-infected individuals." (PMID 34835417, 2021). "In particular, the group infected with PPRV followed by GTPV was the most significant, but compared with the group infected with GTPV alone, the mRNA expression levels of TNF-α, IL-6, and IL-10 in all co-infection groups were inhibited." (PMID 33827620, 2021). "Using different subtypes of flu-viruses (H1N1 and H3N2; two strains for each, lower row) revealed that co-infection with SARS-CoV-2 also induced just a slight increase in IL-6 production by all cell types tested." (PMID 34122407, 2021). "Compared with the group infected with PPRV alone, the mRNA expression levels of TNF-α, IL-6 and IL-10 were enhanced in all co-infection groups." (PMID 33827620, 2021).
co-infection (continued). "High levels of IL-6 were detected in patients with HIV/TB co-infection before initiation of dual therapy (2.1-fold increase vs. HIV), which persisted even after 6 months of treatment (8.96-fold increase vs. HIV), unlike other cytokines." (PMID 34835417, 2021). "Our findings demonstrated that co-infection resulted in higher levels of mRNA levels of Gal-1, Gal-3, IFNγ, IL-6, and iNOS in the liver of co-infected mice compared with PbANKA-mono-infection." (PMID 32883347, 2020). "Microscopic analysis of the pathological features of co-infection in the lungs from WT and IL-6−/− mice showed large lesions; destruction of alveolar structures and vessels; inflammatory cells infiltration and degeneration, and shedding of airway epithelium." (PMID 32038632, 2019). "Co-infection with C. albicans and P. aeruginosa revealed significant upregulation of the proinflammatory cytokine IL-6 and a less prominent increase of IL-8, a potent chemoattractant of neutrophils in a zebrafish in vivo model." (PMID 31623187, 2019). "IL-6 defects resulted in a marked increase in inflammatory cells (mainly neutrophils, approximately 86.3%) in the lungs after co-infection." (PMID 32038632, 2019). "As expected, IL-6 deficiency appeared to impair macrophage phagocytic function during co-infection, while treatment with recombinant IL-6 significantly enhanced macrophage activity." (PMID 32038632, 2019). "In order to test this prediction, mice were simultaneously treated with the neutralizing antibodies for both IFN-γ and IL-6 through administration to the respiratory tract during co-infection." (PMID 31474978, 2019). "Among PWH, HCV coinfection is associated with significant elevations in the monocyte activation markers soluble CD14 and IL-6, suggesting that HCV independently contributes to intestinal barrier damage." (PMID 31304190, 2019). "Significant positive correlations were identified between IFN-γ verses TNF-α and IL-6 verses IL-10 in co-infection (Spearman’s P < 0.05)." (PMID 31687034, 2019). "Significant positive correlations were observed between IFN-γ with TNF-α (Spearman r = 0.847) and IL-6 with IL-10 (Spearman r = 0.557) among co-infection." (PMID 31687034, 2019). "To this end we assessed the effect of the neutralization of IFN-γ and/or IL-6 during co-infection with IAV and S. pn." (PMID 31474978, 2019). "In our severe model, IFN-γ and IL-1β were upregulated, while IL-10 was down-regulated during co-infection in IL-6−/− mice." (PMID 32038632, 2019). "Taken together, these results showed that IL-6 not only affected the death of lung inflammatory cells but also improved macrophages phagocytic functions by increasing MARCO expression during co-infection." (PMID 32038632, 2019). "Last, exogenous IL-6 treatment significantly inhibited IFN-γ production in IL-6−/− mice during co-infection." (PMID 32038632, 2019). "pneumoniae co-infection at different time points and found evidence, from both animal models and partial clinical data, for protective functions of IL-6 during co-infections." (PMID 32038632, 2019). "In this study, a positive correlation between IL-6 and IL-10 elevated levels during co-infection was observed." (PMID 31687034, 2019). "Coinfection with HIV was associated with higher levels of sFas, TNF-α, and sPD-L1 (P < 0.005), and higher levels of the pro-inflammatory cytokines IL-6, IL-8, and IL-12p70 (P < 0.05) compared to healthy controls." (PMID 30815625, 2019). "This review briefly discusses patterns of selected cytokine (IL-6, IL-8, IL-10, TNF-α and INF-γ) responses associated with infections caused by Plasmodium, intestinal parasites as well as a Plasmodium-helminth co-infection." (PMID 29970128, 2018). "It is known that levels of inflammatory mediators such as IL-6 and IL-18 were higher in the patients with co-infection of influenza virus and bacteria than in patients with bacterial pneumonia or influenza virus infection alone." (PMID 30551738, 2018).
co-infection (continued). "The levels of IL-6, IL-10 and G-CSF were elevated in mono-infection and increased further in co-infection." (PMID 29736763, 2018). "We found that simultaneous co-infections result in the selective inhibition of CHIKV replication and an increase in cytokines associated with disease severity such as TNF-α and IL-6." (PMID 28644900, 2017). "In contrast, IL-6 was upregulated during co-infection when compared to DENV particle-matched mono-infection (1.72 fold, p = 0.047) but not to that of CHIKV." (PMID 28644900, 2017). "In CF-patients with chronic S. aureus cultures, independent risk factors for worse lung function are high bacterial density in throat cultures, exacerbations, elevated IL-6 levels, presence of S. aureus SCVs and co-infection with S. maltophilia." (PMID 27861524, 2016). "Decreased levels of IFN-γ, TNF, IL-6, and IL-10 were observed in the serum of co-infected groups, demonstrating a modulation of Malaria immune response by Leishmania co-infections." (PMID 27446022, 2016). "Lately, a newly characterized KSHV-associated condition, abbreviated as KICS (KSHV Inflammatory Cytokine Syndrome) has been reported in patients with HIV and KSHV co-infection, displaying elevated levels of interleukin-6 (IL-6) production." (PMID 25594835, 2015). "Our results showed that although the greatest suppression occurred following overnight infection (18 and 24 h), co-infection with F. tularensis led to significant decreases in IL-6 cytokine suppression as early as 4 h after infection." (PMID 24783062, 2014). "Our results confirm that IL-6 and CRP are strongly associated with paradoxical IRIS in the context of HIV/TB co-infection, even after adjustment for other risk factors." (PMID 23691062, 2013). "The high levels of IL-6 released by infected macrophages have implications for co-infection with HIV." (PMID 16504020, 2006). "Coinfection suppresses the type I interferon (IFN) response, activates the inflammasome and associated pathways, and concurrently triggers the massive secretion of pro-inflammatory cytokines (e.g., IL-6, TNF-α, IL-1β)." (PMID 41561948, 2025). "And IL6 > 388.9 pg/mL and IL4>0.535pg/mL were independent risk factors for co-infection." (PMID 40416960, 2025). "However, this dampening effect that PA seems to have had on IL-6 response when co-infection has occurred is unexpected." (PMID 40788668, 2025). "Additionally, our co-infection model enhances IL-6 production, further amplifying the effects induced by the probiotic mix and vitamin D." (PMID 40351306, 2025). "Co-infection of SCoV2 and H1N1 caused an elevation in the IL-6 and IL-8 concentrations compared with the SCoV2 single infections, while the co-infection of SCoV2 and H5N1 caused an elevation in the IL-6, IL-8, IP-10, RANTES, and TNF concentrations than SCoV2 infection." (PMID 40431161, 2025). "In an IAV-Streptococcus pneumoniae co-infection model, IL-6 was shown to reduce cell death in the lungs and enhance bacterial phagocytosis through upregulation of MARCO expression in macrophages, limiting infection-related inflammation and controlling bacterial invasion." (PMID 40692679, 2025). "Our findings suggested that HIV co-infection in LTB-positive individuals is associated with the diminished production of PPD-induced Th1 (IFN-gamma and IL-2) cytokines by PBMCs and in the plasma level of IL-2 and proinflammatory cytokines (IL-6 and TNF-alpha)." (PMID 39514524, 2024). "Nine variables, including age, preterm birth, underlying condition, seizures, neutrophil-lymphocyte ratio (NLR), interleukin-6 (IL-6), lactate dehydrogenase (LDH), D-dimer, and co-infection, were eventually confirmed as the independent risk factors of RSV-associated SALRTI." (PMID 39114651, 2024). "We found that HIV co-infection in LTB-infected individuals caused a significantly lowered production of PPD-induced Th1 (IFN-gamma and IL-2) cytokines by PBMCs and the systemic pro-inflammatory (TNF-alpha and IL-6) cytokines in plasma." (PMID 39514524, 2024).
co-infection (continued). "In addition, a reduced level of mRNA expression of the cytokines IL-1α, IL-6 and IFNα was observed during co-infection compared to single infection." (PMID 39772252, 2024). "Compared to the non-severe group, more frequent underlying condition, wheezing, and seizures, as well as higher fever peak were observed in the severe group, with higher levels of leukocyte count, NLR, CRP, PCT, IL-6, IL-10, D-dimer, and more frequent co-infection (all P < 0.05)." (PMID 39114651, 2024). "IL-6 and IFNα showed contrasting expression depending on co-infection with SARS-CoV-2 or AdV2." (PMID 39772252, 2024). "In addition, we found that the ICU patients with co-infection had significantly higher levels of IL-6 and IL-10 than those with ICU-acquired infection." (PMID 38249419, 2023). "Furthermore, compared with ICU-acquired infection patients, co-infection group had a significantly higher levels of serum IL-6 (9.58 [6.02–54.61] vs. 0.00 [0.00–29.64], p = 0.022) and IL-10 (34.37 [12.79–693.04] vs. 9.86 [2.79–44.64], p = 0.034)." (PMID 38249419, 2023). "Despite the fact that the level of IL-6 is elevated only slightly, the results show differences among patients with persistent co-infection in the latent and in the active phase, which can be observed only by analysing certain ME/CFS patients’ groups with co-infection." (PMID 36653846, 2023). "The concurrent increase of IL-6 and IL-8, on the other hand, should signal bacterial and fungal infections in patients.These findings may help to suggest bacterial or fungal co-infection in patients with AA (Focus on VSAA and SAA)." (PMID 36319826, 2022). "Interestingly, this increase in IL-6 production was most pronounced upon co-infection of M2 macrophages." (PMID 34122407, 2021). "IL-6, an important pro- and anti-inflammatory cytokine, was described to be significantly upregulated in influenza virus and S. pneumoniae as well as S. aureus co-infections." (PMID 34067487, 2021). "However, we should note that the ECMO supported patients got more severe CO2 retention and acidosis, had higher plasma Il-6 concentrations, and had higher co-infection rate." (PMID 34712673, 2021). "The activation of MAPK p38 in influenza virus single or co-infections with S. pneumoniae or S. aureus was shown to play an essential role in the production of cytokines, such as IFNβ, IL-1β, tumor necrosis factor α (TNFα) and IL-6, in vitro and in vivo." (PMID 34067487, 2021). "Moreover, the mRNA expression levels of IL-6 in the FAdV-only group were significantly higher than those in the IBDV-FAdV co-infection group at 1 and 3 dpi with FAdV-4-HB1501 (p < 0.05)." (PMID 33926543, 2021). "We also compared the dynamic changes of IL-6 in co-infection and single infection." (PMID 32038632, 2019). "IL-6−/− mice presented with increased bacterial burden, early dissemination of bacteria to extrapulmonary sites accompanied by aggravated pulmonary lesions and high mortality when co-infection." (PMID 32038632, 2019). "Our studies also found that IL-6 concentration is significantly higher in co-infection of IAV-S." (PMID 32038632, 2019). "Thus, here we sought to clear if IL-6 contributes to lung pathology or physiology during co-infection." (PMID 32038632, 2019). "Therefore, neutralization of IFN-γ and/or IL-6 was performed in a low bacterial dose co-infection model (1 × 103 CFU)." (PMID 31474978, 2019). "The role of IL-6 in co-infection may be dependent on the influenza strain and the pathology of the virus." (PMID 32038632, 2019). "Primary IAV infection promoted cellular apoptosis in the lung and IL-6 deficiency was not conducive to lung inflammatory cell survival, especially during co-infection." (PMID 32038632, 2019).